STAT3 (signal transducer and activator of transcription 3)
Diseases named in the same sentence as STAT3 in open-access papers (continued):
Sharing a sentence is not in itself a finding about the gene and the disease.
cancer (continued). "CUR exerts its effects by downregulating multiple cell signaling pathways, which include NF-κB, STAT3, activated protein-1 (AP-1) and epidermal growth response-1 (Egr-1), which are all crucial in the development and progression of cancer." (PMID 30890933, 2019). "Using gain-of-function and loss-of-function strategies, we further clarified the impact of 14–3-3ζ/HO-1 complex on the signal transducers and activators of transcription 3 (STAT3) signaling pathway in cancer cells." (PMID 30606233, 2019). "The mRNA levels of STAT3 were 2.1-fold higher in carcinoma tissue than in control mucosa, respectively." (PMID 31781300, 2019). "It has been reported that the AKT, ERK, JNK, and STAT3 pathways were related to the evolution and progression of carcinoma mediated by the CXCL5/CXCR2 axis." (PMID 30792394, 2019). "Recently, Debio 0617B is the first-in-class kinase inhibitor that targeting phospho-STAT3 (pSTAT3) and/or pSTAT5 specifically in carcinomas by suppressing the activity of JAK, SRC, ABL, and class III/V receptor tyrosine kinases (RTK)." (PMID 30847297, 2019). "The role of STAT3 in protein muscle catabolism was further elucidated in a subsequent study using several mouse models of cancer cachexia." (PMID 30081609, 2018). "Interleukin-6 (IL-6) is known to stimulate STAT3 phosphorylation on tyrosine Tyr705 in many cancer cells." (PMID 30577812, 2018). "STAT3, a promising molecular target for cancer therapies, is a member of the STAT family of transcription factors that mediate cellular responses to cytokines and growth factors." (PMID 29849942, 2018). "Given the clear importance of the JAK–STAT pathway and their interplay with chromatin remodeling enzymes in the initiation and progression of cancer, targeting of STAT3 and/or STAT5 is of high therapeutic relevance." (PMID 29728695, 2018). "In KRAS mutant PDA mouse models, STAT3 inhibition resulted in tumor volume reduction and decreased cancer cell proliferation." (PMID 29891787, 2018). "Targetting STAT3 in cancer treatment has shown therapeutic benefits in both preclinical and clinical studies." (PMID 29326301, 2018). "Comparing whole gene expression profiles using PANTHER and NetworkAnalyst in combination with RNAseq, we determined the role of STAT3 activation in CRC-derived cancer stem-like tumorspheres." (PMID 30068339, 2018). "STAT3 is reported to be active in various cancer cell types, and it is primarily involved in the transcriptional regulation of apoptosis, inflammation, and invasiveness." (PMID 29757235, 2018). "In accordance with this, inactivation and inhibition of Stat3 signaling have been shown to be involved in the inhibition of cell growth and progression in several cancer types, including lung cancer." (PMID 30209296, 2018). "We conducted cDNA microarray analysis by using the Oncomine database to explore gene expression of STAT3 in cancer types." (PMID 29423040, 2018). "While in normal cells, STAT3 activation is strictly controlled; in cancer cells, it is persistently activated." (PMID 29576846, 2018). "Many cytokines, growth factors and G-protein coupled receptors induce Y705-STAT3 phosphorylation, demonstrating that diverse pathways lead to constitutive STAT3 activity in cancer." (PMID 29774125, 2018). "S3I-201 blocks STAT3 function in cancer cells by binding to the STAT3 SH2 domain to disrupt STAT3 protein complexation events." (PMID 30186159, 2018). "Overall, high levels of both STAT3/5 activity are found in most cancer types or stroma cells surrounding MPN or PTCL cells." (PMID 29148847, 2018). "Enhanced STAT3 activity, reported in various human tumors, promotes cancer cell survival via therapeutic resistance." (PMID 30442941, 2018). "Upstream kinases, such as JAKs, are among the STAT3 pathway components that have been targeted for cancer therapy." (PMID 29914167, 2018). "Activated STAT3 in cancer cells binds to the NF-κB complex proteins RelA/p65 and the histone acetyltransferase p300 in the nucleus." (PMID 30279347, 2018).
cancer (continued). "STAT3 was observed to be hyperactive in cancer where it promotes tumorigenesis by enhancing cell proliferation and angiogenesis in various malignant tumors including liver, lung, and breast cancers." (PMID 29921768, 2018). "Here, we will review the PTPs that have been implicated in the inactivation of STAT3, with an emphasis on PTP regulation of STAT3 signaling in cancer." (PMID 30208623, 2018). "We took a further look into the activation status of STAT3 in six representative cancer cells lines." (PMID 29921758, 2018). "In vitro treatment with Hst on various cancer cell lines showed significant down-regulation of IL-6 induced p-STAT3 (Tyr705) expression." (PMID 29963254, 2018). "In the present study, we demonstrated that Wwox impedes the association of JAK2 with STAT3, thereby inhibiting STAT3 phosphorylation and p-STAT3-dependent cancer cell growth in vivo." (PMID 30154439, 2018). "In all three cancer cell lines, STAT3 (phospho Y705) was also reduced after 1 h CBD (5 μM) treatment; again this reduction was higher in PC3 and HEPG2 cells, compared to the MDA-MB-231 cells." (PMID 30150937, 2018). "Leptin also induces the expression of TFs associated with the maintenance of the cancer stem cell phenotype, such as NANOG, SOX2, and OCT4 in a STAT3-dependent manner, promoting a more aggressive phenotype of cancer cells." (PMID 30404206, 2018). "It should be noted that STAT3 also plays an important role in the regulation of cancer stem cells and therapy resistance." (PMID 30301213, 2018). "Constitutively active STAT3 is often encountered in several types of cancer cells including MM and plays a pivotal role in cancer cell survival and proliferation." (PMID 29899697, 2018). "Although abundant evidence suggests that STAT3 is an ideal target for cancer therapy, to date, effective therapeutic interventions to inhibit STAT3 and generate a potent antitumor effect clinically remain to be explored and developed." (PMID 30186159, 2018). "Persistent activation of STAT3 is frequent in maligned cells, and STAT3 signaling induced the expression of genes that are important for cancer inflammation." (PMID 30235866, 2018). "Inside the cell, EGFR is imported to the nucleus by Importin β1 and associates with activated STAT3, and potentially other transcription factors, to induce the expression of nuclear EGFR target genes, thereby promoting cancer cell proliferation." (PMID 29599917, 2018). "Compounds identified from AC have been reported to inhibit the phosphorylation of JAK2 and STAT3 in cancer cells." (PMID 30618745, 2018). "The IL-6/STAT3 paracrine signaling pathway from TAMs also triggers the proliferation of cancer progenitor cells to facilitate hepatocarcinogenesis." (PMID 30104473, 2018). "Studying the relationships of p63 with STAT3 and generally the role of p63 in cancer needs careful assessment of isoforms that are being expressed." (PMID 29588647, 2018). "STAT3 is found constitutively phosphorylated in a number of human cancer cell lines and primary tumors." (PMID 30577812, 2018). "As active STAT3 has been reported to be essential for regulating the CSCs of a number of cancers including CRC41, we next examined the effects of regorafenib, SC-43, and SC-78 on the stemness properties of both HCT-116 and HT-29 cells." (PMID 30109144, 2018). "This review summarizes STAT3 function and regulation, its role in stem cell and cancer stem cell properties and highlights recent reports about its relationship to p63." (PMID 29588647, 2018). "Inhibition of STAT3 has been found to increase radiation sensitivity in cancer cells, and to inhibit radiation-induced progression in glioma." (PMID 29439394, 2018). "This first-in-class cancer stemness inhibitor targets STAT3 driven gene transcription and spherogenesis of the cancer stem cell." (PMID 29382159, 2018).
cancer (continued). "Studies have also indicated that restoring or overexpressing PIAS3, via repression of STAT3‐mediated oncogenic pathways, shows inhibitory effects on cancer cells." (PMID 30259640, 2018). "We used both targeted cancer-related gene arrays and RNA-seq to investigate the role of STAT3 in gene regulation." (PMID 29774125, 2018). "STAT3 is a key master regulator that controls cancer proliferation and invasion, and thus we selected this protein for further study." (PMID 30001751, 2018). "Due to the inhibitory activity of NF-κB or STAT3, boswellic acid analogue was shown to inhibit the growth and metastasis of human colorectal cancer in nude mice through downregulation of cancer proliferation, invasion, angiogenesis, etc.." (PMID 29784005, 2018). "Most of the studies focused on elucidating the anti-cancer mechanisms such as apoptosis induction, angiogenesis inhibition, drug resistance reduction by targeting NF-κB and/or STAT3." (PMID 29784005, 2018). "In this article, we summarize the available data about the function of STAT3 interactors in malignant cells and discuss their role as potential therapeutic targets for cancer treatment." (PMID 29914167, 2018). "Given the crucial role of phosphorylation of this site for HPV containing keratinocyte proliferation, we further investigated STAT3 protein expression and phosphorylation levels in HPV associated cancers." (PMID 29630659, 2018). "Among these genes, notably, platelet-derived growth factor A (PDGFA) and signal transducer and activator of transcription 3 (STAT3) were relevant according to the cancer pathway analyzed using NetworkAnalyst." (PMID 30068339, 2018). "As an important signaling molecule for many cytokines and growth factor receptors, constitutive activation of Stat3 occurs at a high frequency in many types of cancer." (PMID 30209296, 2018). "Many regulatory molecules that are involved in EMT, including Snail, Dlx-2, HIF-1α, STAT3, TGF-β, Wnt, and Akt, have been implicated in the metabolic reprogramming of cancer cells." (PMID 30671168, 2018). "Our results suggest that HDAC3 is an important regulator of STAT3-dependent cell proliferation in liver regeneration and cancer." (PMID 29540666, 2018). "Signal transducer and activator of transcription (STAT)-3 is activated in many cancers, where it promotes growth, inflammation, angiogenesis, and inhibits apoptosis." (PMID 29890775, 2018). "Constitutive activation of the STAT3 signaling pathway plays a critical role in tumorigenesis and cancer progression in humans via promotion of cancer cell growth, survival, migration, and invasion." (PMID 30442941, 2018). "Niclosamide has been shown to have anticancer activity in previous reports, which attributed to the anti-cancer activity to its inhibitory effects on Wnt- or Stat3- pathways or on S100A414,20,47." (PMID 29440715, 2018). "The self-renewal of stem cells has a regulatory mechanism that is similar to that of the proliferation of cancer cells and STAT3 is an essential component of this mechanism in embryonic stem cells and various types of stem cells and cancer stem cells." (PMID 30026553, 2018). "This is consistent with previous observations showing increased STAT3 Y705 phosphorylation in HPV-positive cancer cell lines, and leading to increased levels of STAT3-dependent gene products." (PMID 29630659, 2018). "In the following years, accumulating research pinpointed the role of this STAT3 suppressor as a promising therapeutic target in different cancer types." (PMID 29914167, 2018). "Pre-treatment of cancer exosomes with SC144 decreased both exosome-mediated phosphorylated STAT3 levels and nuclear translocalization in BMDMs." (PMID 29867925, 2018). "Recent studies have highlighted critical roles of the master transcription factors nuclear factor κB (NF-κB) and signal transducer and activator of transcription 3 (STAT3) in linking inflammation to cancer development." (PMID 30143645, 2018).
cancer (continued). "Signal transducer and activator of transcription 3 (Stat3) is overexpressed in many cancers; STAT3 has been shown to be involved in the regulation of CAIX expression in several studies." (PMID 29439394, 2018). "Remarkably, IL-6, IL-10, CXCR4, and CCL2 mRNA, which are all STAT3 target genes involved in cancer progression, were increased in macrophages exposed to exosomes." (PMID 29867925, 2018). "The activated STAT3 then stimulates the expression of cancer-related target genes, including VEGF, c-myc, MMP-9 and Mcl-1, and promotes human hepatocyte viability." (PMID 32201498, 2018). "The expression of oncogenes like Src, K-ras and Bcr-Abl, growth factors and cytokine receptors can persistently activate STAT3, thereby leading to cellular transformation or promoting cancer cell survival." (PMID 29921770, 2018). "Particularly, STAT3 is a critical regulator of EMT-associated, CSC-like properties in various cancer cells." (PMID 30013043, 2018). "JAK2 is the major kinase of STAT3 and has been reported to be constitutively active in many cancers and other proliferative diseases." (PMID 29921758, 2018). "To date, many studies have showed that the IL-6/Janus kinase/STAT3 signaling pathways are involved in drug resistance, angiogenesis, migration, and other processes in cancers." (PMID 30202238, 2018). "Targeting STAT3 is an appealing anti-cancer strategy and the multi-step process of STAT3 activation allows multiple points for inhibiting its oncogenic functions." (PMID 29914167, 2018). "PN has been reported to exhibit inhibitory activity on the IL-6-induced STAT3 activation, which contributes to its anti-inflammation and anti-cancer properties." (PMID 29921758, 2018). "Conversely, disruption of STAT3 signaling by antisense oligonucleotides or STAT3 mutants results in growth inhibition and induction of apoptosis in various types of cancer cells." (PMID 29686295, 2018). "Patients with cancer have systemic elevations of cytokines that signal via STAT3 leading to increased IR expression in naïve, peripheral CD8+ T cells making them poised for exhaustion even before TCR binding." (PMID 30400822, 2018). "Translating CS3D to the clinic will augment current treatment strategies for cancers that are characterized by dependence on STAT3 signaling." (PMID 29848966, 2018). "In contrast, the immunosuppressive activity of human MDSCs derived from patients with cancer was found to be STAT3-dependent." (PMID 30075733, 2018). "As STAT3 is strongly activated in several cancer cell types, we compared STAT3 activation in our GSCs with normal human Neural Stem Cells (H9-hNSC)." (PMID 29423098, 2018). "TLR4 promotes cancer progression by activating several signaling pathways, but M2-CM specifically activated the STAT3 signaling pathway in the present study." (PMID 29338742, 2018). "Another aspect of skeletal muscle metabolism, regulated by IL6/STAT3 pathway in cancer cachexia, is the process of muscle repair via satellite cells recruitment." (PMID 30072615, 2018). "As the phosphorylation of STAT3 leads to the transcriptional activation of gene expression related to cancer aggressiveness, the alteration of STAT3 target genes after the combination treatment of emodin and sorafenib was measured." (PMID 30321984, 2018). "Signal transducer and activator of transcription 3 (STAT3) has been shown to play a critical role in the maintenance of cancer stem cells (CSCs)." (PMID 30109144, 2018). "Altogether, these data indicate the ability of TIP60 to co-repress basal and cytokine-induced STAT3 activity in cancer cell lines in part through the recruitment of HDAC7." (PMID 29914167, 2018). "From a clinical perspective, however, it would be beneficial to target STAT3/14-3-3ζ interaction to inhibit the deleterious cooperation of 14-3-3ζ and STAT3 in cancer cells while sparing some of their essential homeostatic functions." (PMID 29914167, 2018).
cancer (continued). "When starved cancer cells undergo ER stress, NF-κB and STAT3 work together to drive IL-6 expression." (PMID 30186868, 2018). "A further study that specifically elucidates how MSC-CM results in the inhibition of Stat3 and thus regulates the radiosensitivity of cancer cells will be performed in the future." (PMID 30297887, 2018). "STAT3 is an oncogenic transcription factor and is considered as an emerging target for cancer therapy." (PMID 29326301, 2018). "JAK2 activates STAT3/5A/5B transcription factors, which can directly induce target genes to accelerate cell cycle progression, survival, and cancer cell metabolism." (PMID 29148847, 2018). "Recently, it was found that trastuzumab resistance in this type of cancer is promoted through activation of a STAT3/HIF-1α/Hes1 axis via down-regulation of PTEN." (PMID 29588647, 2018). "The bioassay was based on inhibition by IL-22BP of IL-22-induced STAT3 phosphorylation in the A549 cancer cell line." (PMID 30619294, 2018). "For example, dysregulated activation of STAT3 has been observed in many types of cancer cells, so STAT3 is expected to be the effective target for anticancer therapy." (PMID 29402895, 2018). "STAT3 is vital in tumorigenesis and cancer-induced immunosuppression and its persistent activation has been observed in several cancers." (PMID 29976158, 2018). "This review will now focus on STAT3’s involvement in signaling pathways regulating stem cells and cancer stem cells." (PMID 29588647, 2018). "Since CSCs are resistant to traditional therapies including gemcitabine chemotherapy and radiotherapy, targeting the signaling pathways (Hedgehog, NANOG, STAT3) that drive cancer cell stemness represent a strategy against CSCs." (PMID 29891787, 2018). "Recently, STAT3 inhibitors have been shown to enhance the radiosensitivity of cancer cells and to reduce the malignant invasive ability induced by radiation." (PMID 29571296, 2018). "In castration resistant prostate cancer, tumor infiltrating B-cells secrete lymphotoxin (LT) α:β which engages with LTβR on cancer cells and activates the STAT3 pathway to promote androgen-independent cancer cell growth." (PMID 30356678, 2018). "The relationship between STAT3 and Notch1 signaling pathway has been reported in multiply kinds of cancer, either coordination or interaction." (PMID 29872398, 2018). "Our results indicated that MSC-CM reduces the growth of MDA-MB-231 cells and sensitises the cancer cells to radiation therapy through inhibition of Stat3 activation." (PMID 30297887, 2018). "The variety of the receptors triggering this pathway is unmatched among known signaling cascades, and the wide range of downstream proteins indicate the importance of JAK2/STAT3 axis in cancer progression." (PMID 30109213, 2018). "Since PN is a JAK2 covalent inhibitor and can inhibit the IL-6-induced STAT3 activation, we next examined the effect of PN on the IL-6-induced cancer cell migration." (PMID 29921758, 2018). "Emerging evidence has demonstrated the role of STAT3 in cancer progression, invasion and metastasis." (PMID 30001751, 2018). "Like in cancer cells, this effect was persistent through the activation of the IL-6/STAT3/NF-κB positive feedback loop, which is responsible for the persistent activation of BSFs." (PMID 29707149, 2018). "STAT3, a star molecule in cancer progression, can activate other molecules involved in immunosuppression or metastasis." (PMID 30060755, 2018). "Lastly, lncRNA-ATB activates the autocrine induction of IL-11 by binding to IL-11, and then activates STAT3 signaling to promote cancer cell colonization." (PMID 29692736, 2018). "Due to this central role, STAT3 is widely considered a good target for anti-cancer therapy; however, the success of these approaches has been, so far, very limited." (PMID 30231553, 2018).